CD200R1 (CD200 receptor 1)
Diseases named in the same sentence as CD200R1 in open-access papers (continued):
Sharing a sentence is not in itself a finding about the gene and the disease.
lung adenocarcinoma (1 paper, 2023). A carcinoma that arises from the lung and is characterized by the presence of malignant glandular epithelial cells. "In addition, we found that the correlation coefficient between CMTM6 and the other three immune checkpoints (PD-L2, HAVCR2 and CD200R1) in lung adenocarcinoma was higher than that between CMTM6 and PD-L1." (PMID 36643629, 2023). "However, in lung adenocarcinoma, there is no report on the relationship between CMTM6 and PD-L2, HAVCR2 and CD200R1." (PMID 36643629, 2023).
lung disease (1 paper, 2018). "Therefore, our data illustrated that the phenotype of AM taken as a whole, without considering each lung disease separately, was closer to GM-MDM (similar expression of CD163, CD169, CD200R1) than to M-MDM phenotype." (PMID 29562615, 2018).
metastatic cancer (1 paper, 2019). A carcinoma which has spread from the original site of growth to another anatomic site. "Importantly, CD200R1 was overexpressed in stromal cells of the metastatic cancer patients compared to patients without metastases (p=0.002)." (PMID 30800162, 2019).
Nephroblastoma (1 paper, 2024). An embryonal neoplasm characterized by the presence of epithelial, mesenchymal, and blastema components. "Finally, the results showed that there were significant differences in CD80, CD48, IDO2, CD276, CD28, and CD200R1 between both groups, which could be used as potential therapeutic targets for the treatment of nephroblastoma." (PMID 38526609, 2024).
osteoarthritis (1 paper, 2022). A noninflammatory degenerative joint disease occurring chiefly in older persons, characterized by degeneration of the articular cartilage, hypertrophy of bone at the margins and changes in the synovial membrane. "This aptamer recognizes both human and mouse CD200R1 and thus can be evaluated in murine models of inflammation, including osteoarthritis." (PMID 35359946, 2022). "CD200R1 are found on macrophages and macrophages are highly expressed, albeit in a cyclic manner, during the entirety of osteoarthritis." (PMID 35359946, 2022).
preeclampsia (1 paper, 2022). Preeclampsia is a hypertensive disorder of pregnancy that is characterized by new-onset hypertension with proteinuria presenting after 20 weeks of gestation, and depending on mild or severe forms may initially present with severe headache, visual disturbances, and hyperreflexia. "Another study utilizing another group of multiple preeclampsia gene sets showed mainly immune-related genes (bone morphogenetic protein 5 (BMP5), cell surface glycoprotein (CD) 200R1 (CD200R1) and 28 (CD28), and TLR7) that are differentially expressed in preeclampsia." (PMID 35269385, 2022).
pulmonary fungal infection (1 paper, 2019). "CD200R1 therefore alters the magnitude, but not phenotype of fungal lung disease." (PMID 31365119, 2019).
trauma (1 paper, 2022). "Most intriguingly, local CD200R1 inhibition by the blocking antibody determined a less inflammatory microenvironment after PNS trauma, in contrast to the pro-inflammatory microenvironment described after CD200R1 inhibition with the same antibody after CNS trauma." (PMID 35681481, 2022).
tumor (86 papers, 2012 to 2026). "Loss of CD200R1 expression resulted in decreased tumor-infiltrating CD8+ cells and enhanced the secretion of inflammatory cytokines." (PMID 40075669, 2025). "They found that CD200 overexpression in the host was associated with diminished primary tumor growth and metastasis, while loss of CD200R1 expression by host cells was linked to increased visceral metastasis." (PMID 40075669, 2025). "To confirm the association between CD200R1 expression and lymphocyte infiltration in tumor tissue, we examined TCGA patient cohorts with matched histology-based lymphocytes infiltration scores and gene expression data." (PMID 32635224, 2020). "Cox regression analysis of CD200R1 expression could improve our understanding of the biological role of CD200R1 in cancer as CD200R1 signaling is associated with tumor growth and metastasis." (PMID 32635224, 2020). "Indeed, the livers of these CD200R1-deficient mice exhibited increased metastatic CD200+ tumor growth which contained higher numbers of CD11b+Ly6C+ myeloid cells, displayed VEGF and HIF1a gene expression with increased angiogenesis, and showed significantly reduced CD4+ and CD8+ T cell infiltration." (PMID 32635224, 2020). "Tumor tissue from 20 participants (71%) were evaluable for CD200R1 expression, and 19 of 20 (95%) had detectable immune cell expression of CD200R1." (PMID 39651931, 2025). "The expression of CD200 and CD200R1 was evaluated by IHC in FFPE archival or baseline tumor biopsy samples collected from study participants." (PMID 39651931, 2025). "This FIH study for 23ME-00610 achieved well-tolerated doses that are likely to completely inhibit CD200R1 in the tumor." (PMID 39651931, 2025). "Once again, growth of the highly metastatic 4THM tumor occurred in both CD200RKO mice and WT mice after primary tumor resection along with CpG/tumor cell immunization, even when, in WT mice, resection was followed by iv infusions of Fab anti-CD200R1." (PMID 38540350, 2024). "Anti-CD200R1 monoclonal Ab inhibits tumor volume in mice inoculated with murine Hepa1–6 cells, suggesting that the CD200–CD200R pathway is involved in HCC tumor growth." (PMID 37894750, 2023). "We demonstrated that P4HA1 expression was positively correlated with the expression of TNFSF15, CD80, VTCN1, TNFSF18, and CD200R1 in multiple tumor types but negatively correlated with the expression of CD40LG and CD244." (PMID 35812752, 2022). "In one study on patients with NSCLC, CD200/CD200R1 expression in tumor and stroma was investigated with IHC, and high CD200R1 expression was associated with worse survival." (PMID 33918618, 2021). "Significantly lower CD200R1 expression (Welch’s t-test, p < 0.001) was observed in the tumor tissue than that in normal tissue." (PMID 32635224, 2020). "To explore the role of CD200R1 in HNSCC, we determined CD200R1 mRNA expression in normal and tumor tissues in TCGA datasets from the University of California, Santa Cruz Xena platform." (PMID 32635224, 2020). "CD8A, DOK2, CX3CR1, TYROBP, CXCL9, CD300LF, and IFNG were identified as significant DEGs between tumor samples with high and low CD200R1 expression." (PMID 32635224, 2020). "Samples with higher CD200R1 expression displayed higher tumor-infiltrating immune cell counts both in silico and in histological analysis." (PMID 32635224, 2020). "CD200R1 deficiency was found to alter the tumor microenvironment (TME), leading to accelerated tumor growth and reduced T cell infiltration and/or effector function, while CD200R1 expression was significantly lower in HNSCC tumors than that in normal tissues." (PMID 32635224, 2020). "In particular, we demonstrated that patients with HNSCC and high tumor tissue CD200R1 mRNA expression displayed significantly better OS than those with low CD200R1 expression." (PMID 32635224, 2020). "Our most important finding was the correlation between metastatic pattern and high expression patterns of CD200 on tumor cells together with CD200R1 expression on stromal cells." (PMID 30800162, 2019).
tumor (continued). "The results of immunohistochemical analysis showed a strikingly high level of CD200 in tumor cells (p=0.001) and CD200R1 expression in normal mucosal epithelium and stromal cells." (PMID 30800162, 2019). "More than that, 87% of metastatic patients had a phenotype of upregulated CD200 in tumor cells accompanied by overexpressed CD200R1 in stromal cells." (PMID 30800162, 2019). "CD200 imparts an immunoregulatory signal through its receptor, CD200R1, leading to the suppression of tumor specific immunity." (PMID 30800162, 2019). "We report growth and metastasis of both EMT6 and a highly metastatic 4THM tumor in WT mice receiving iv infusions of Fab anti-CD200R1 along with CpG/tumor cell immunization." (PMID 25409195, 2014). "Analysis of participant tumors suggested that patients with high tumor CD200 expression may be more likely to have clinical benefit with CD200R1 inhibition, which suggests promise as a predictive biomarker for efficacy." (PMID 39651931, 2025). "The trend for clinical benefit in participants with tumor CD200 expression suggests that 23ME-00610 inhibits CD200R1 signaling and may reverse CD200-mediated immune evasion." (PMID 39651931, 2025). "Furthermore, variability of tumor expression of CD200R1 among lesions and between tumor types, similar to PD-1, can result in an additional ∼2-fold difference in drug uptake based on target expression." (PMID 39651931, 2025). "WT mice could be cured of EMT6 growth by surgical resection in the same fashion as CD200RKO mice if primary tumor resection was followed by iv infusions of Fab anti-CD200R1 along with CpG/tumor cell immunization." (PMID 38540350, 2024). "CD200 interacts with its receptor CD200R1 to trigger immunosuppressive signals, resulting in macrophage suppression, regulatory T cell induction, cytokine profile switching from Th1 to Th2, and finally the inhibition tumor-specific T-cell immunity." (PMID 34136486, 2021). "Our current data also disclose a mechanism by which CD200:CD200R1 affects tumor progression and may strengthen the feasibility of targeting CD200 or CD200R1 as anticancer strategy." (PMID 30800162, 2019). "Through this endogenous inhibitory pathway, CD200:CD200R1 interaction may also be featured in tumor progression, outgrowth, and/or metastasis." (PMID 30800162, 2019). "In the EMT6 model, increased immunosuppression and attenuation of an inflammatory response (by increased signaling through CD200:CD200R1 in CD200tg mice, or with CD200tg tumor cells 13) led to increased metastasis, while the reverse was the case in CD200R1KO mice." (PMID 26725371, 2016). "In addition, a soluble form of CD200 (sCD200), released following CD200 ectodomain shedding by matrix metalloproteinase-1 (MMP1) and ADAM19 metallopeptidase, is able to engage CD200R1, can be quantified in the serum, and has been correlated with worse tumor prognosis in CLL and GBM patients." (PMID 40904466, 2025). "Moreover, tumor CD200R1 expression was strongly correlated (Spearman’s ρ > 0.5) with the expression of at least one of four commonly used T cell and myeloid infiltration markers (CD4, CD8A, CD11B and CD45) in tumors from multiple cancer types in The Cancer Genome Atlas (TCGA;)." (PMID 40428397, 2025). "Thus, targeting CD200R1 for breaking CD200/CD200R1 immune tolerance in cancer presents an opportunity to target multiple immune cell populations in addition to T cells in the tumor, such as myeloid and NK cells, which has been shown to be a promising approach in preclinical research." (PMID 39651931, 2025). "In addition, FCER2, CD200R1, and RHOV in the signature were strongly associated with the clinical stage of the tumor, and univariate cox analysis showed that except for TNNT2, WT1 and KRTAP5-8, the remaining signature genes were closely correlated with the prognosis of LUAD patients." (PMID 37234773, 2023).
tumor (continued). "The findings demonstrated that cluster 1 has highly expressed immunosuppressive sites such as BTLA, CD200, CD200R1, CD44, HAVCR2, etc. that promote immunosuppression and tumor formation." (PMID 38347320, 2024). "Interestingly, use of CD200fc, which is an CD200R1 agonist, significantly decreased the growth of metastatic breast cancer 4THM cells due to the inhibition of cancer-related inflammation and increase both the tumor-infiltrating CD8+ T cell number and tumor-induced IFN-γ secretion." (PMID 33562512, 2021). "Importantly, we report novel data on immune cell expression of the newly described CD200/CD200R1 pathway, and the leukocyte immunoglobulin-like receptors (LILRs), which may represent novel innate immune checkpoints, dampening the anti-tumor T cell immune response in NSCLC." (PMID 33918618, 2021). "For that reason, we assessed the relationship between expression patterns of tumor cell proliferation marker Ki-67 and CD200:CD200R1." (PMID 30800162, 2019). "The CD200/CD200R1 axis has been shown to be involved in the expansion of the MDSC population and tumor proliferation, and different studies have suggested that inhibition of this axis could enhance the efficacy of immunotherapy." (PMID 40904466, 2025). "CD200R1 is a member of immunosuppressive receptors principally expressed in immune cells such as CD4+/CD8+ T cells and myeloid cells, while its ligand CD200 is present in various normal and tumor cells." (PMID 40936767, 2025). "The CD200:CD200R1 interaction could modulate the TME, accelerating tumor growth and metastasis." (PMID 40936767, 2025). "In addition, in the tumor microenvironment, we found that PPRC1 expression in LIHC and OV had the same trend as some immune-cell molecular markers such as CD200, CD200R1, and LAIR1, although, in SKCM we found that PPRC1 expression had the opposite trend to that of some immune cell molecular markers." (PMID 37109742, 2023). "Additionally, investigators demonstrated in vivo that CD200AR-L downregulates the expression of CD200R1 in wild-type mice but not in mice lacking DAP10, which was found to be specifically involved in tumor growth regulation." (PMID 36756156, 2023). "However, such high CD200R1 expression was not seen for CD8 T cells, suggesting that CD200-CD200R1-mediated immune evasion is not a mechanism that affects CD8 T cell anti-tumor responses." (PMID 40568095, 2025).
cancer (49 papers, 2012 to 2026). A tumor composed of atypical neoplastic, often pleomorphic cells that invade other tissues. "We focused our research on the CD200/CD200R1 axis, recently pointed out as potential targets in some forms of cancer." (PMID 40904466, 2025). "We next generated a dormancy gene signature from our findings that included the expression levels of SLURP1, INFGR2, KLF4, and CD200 in cancer cells along with CD200R1 in NK cells and tested for links to immunotherapy responses." (PMID 40568095, 2025). "Genome-wide association studies (GWAS) of the 23andMe genetic database identified CD200R1 as a promising therapeutic target for cancer." (PMID 39651931, 2025). "Using the deconvolved TCGA-BRCA dataset, we found that patients with high CD200 levels in cancer cells also showed high levels of CD200R1 in NK cells, CD14+ myeloid cells, and Treg, consistent with our observations in mouse models." (PMID 40568095, 2025). "Previous study has been reported that it was considered a viable therapeutic target in cancer by blocking CD200R in the CD200R1 pathway." (PMID 36084049, 2022). "Consequently, CD200/CD200R1 blockade has recently been considered a potential target in some forms of cancer." (PMID 40904466, 2025). "Therefore, further Pearson analysis was conducted to investigate the correlation between GPR65 and common cancer immune checkpoint inhibitors, such as CD200R1, CD47, HAVCR2, TIGIT, CTLA4, LAG3, and PD1." (PMID 38218960, 2024). "Generally, XIST expression was positively related to about half of these markers in various cancers, such as CD2000, CD200R1, CD274, members of the tumor necrosis factor (TNF) ligand family, and so on." (PMID 36212008, 2022). "Interestingly, genes such as CCDC88C, CD200R1, and CUL3 have been associated with prognosis or being highly expressed in other forms of cancer, however they have not been reported in PDAC to the best of our knowledge." (PMID 25180633, 2014).
infection (28 papers, 2009 to 2025). The state of being infected such as from the introduction of a foreign agent such as serum, vaccine, antigenic substance or organism. "The fact that CD200R1-KO mice exhibit a dramatic susceptibility to infection, only after injury or LPS, highlights the often overlooked importance of these immune signaling pathways in quelling endogenous/exogenous bacterial invasion triggered by brain injury." (PMID 30777093, 2019). "However, the role of immune inhibitory molecules like CD200R1 in the peripheral inflammatory response and susceptibility to infection after brain injury remains largely unexplored." (PMID 30777093, 2019). "Airway macrophages have a higher expression of CD200R1 than did their systemic counterparts, thus apparently avoiding the inflammation that typically results from infection." (PMID 33562512, 2021). "For example, Leishmania amazonensis induce the expression of CD200 both at mRNA and protein level in bone marrow macrophages, which next inhibit neighboring macrophages that express CD200R1, and thus, abrogate NO production during the infection." (PMID 33562512, 2021). "The decreased infection of HSV-1 at all time points in CD200R1−/− MEFs as well as macrophages indicates that the situation is more complex than simply the suppression of a virus-toxic metabolite such as NO, which can be driven or amplified by TLR2." (PMID 23082204, 2012). "In HSV-1, CD200R1 supports infection at or before the stage of early gene expression, which in turn regulates the surface expression of TLR2." (PMID 23082204, 2012). "The expression of ICP8-GFP peaked in CD200R1+/+ cells at 12 h after infection, with over 40% of the cells expressing GFP." (PMID 23082204, 2012). "CD200R1−/− mice, however, continued to have a high percentage of animals (42%) that had completely cleared the infection." (PMID 23082204, 2012). "A large proportion of CD200R1−/− mice were essentially free of replicating virus by day 3–4 post-infection in contrast to CD200R1+/+ mice which continued to produce infectious HSV-1 virions in their brains over the entire 4 day course of the study." (PMID 23082204, 2012). "WT and CD200R1 PCLS showed a similar IL6 induction upon infection with live or heat-killed CHA." (PMID 33250899, 2020). "Elicited macrophages from both CD200R1+/+ and CD200R1−/− mice were infected with HSV-1 (multiplicity of infection; MOI = 10), or challenged with Pam2CSK4 (100 ng/ml), or LPS (100 ng/ml), and levels of IL-6, CCL5 (Rantes), or CCL2 (MCP-1) were measured at 24, 48, and 72 h." (PMID 23082204, 2012). "Importantly, approximately 50% of the CD200R1−/− mice had cleared the infection by days 3 and 4, while HSV-1 continued to replicate at high levels in 100% of CD200R1+/+ mice." (PMID 23082204, 2012). "After infection with S. epidermidis 1457, macrophages predominantly shifted to CD163+/CD200R1+ (CD163+: 66.84% ± 4.95." (PMID 39567551, 2024). "Yet, infection of CD200R1 KO PCLS with live CHA and simultaneous inhibition of MARCO significantly decreased IL6 expression compared to live CHA-infected CD200R1 KO PCLS with functional MARCO signaling." (PMID 33250899, 2020). "The expression of CD200R1 on the surface of WT and TLR2−/− elicited macrophages was determined by flow cytometry 24 h after infection with HSV-1." (PMID 23082204, 2012). "CD200R1+/+ and CD200R1−/− mice were infected with HSV-1 and their brains were harvested and analyzed to assess inflammation 1 and 4 days post-infection." (PMID 23082204, 2012).
neurological disease (7 papers, 2011 to 2022). "In addition, to our knowledge, little attention has been paid to the expression of the different CD200 and CD200R1 mRNA variants or protein isoforms in neurological disorders." (PMID 35296683, 2022). "One of the most innovative findings of our work is that three biomarkers that are also altered in neurological diseases (CD200R1, α2-MRAP, and MATN3) are among the strongest predictors of a negative outcome in the complete model." (PMID 36012423, 2022). "Indeed, we consider that CD200R1 agonists are promising molecules that should be developed to modulate neuroinflammation and the resulting neurotoxicity in neurological disease." (PMID 28522962, 2017).